CDKN2B (cyclin dependent kinase inhibitor 2B)
Diseases named in the same sentence as CDKN2B in open-access papers (continued):
Sharing a sentence is not in itself a finding about the gene and the disease.
osteosarcoma (8 papers, 2009 to 2023). A usually aggressive malignant bone-forming mesenchymal neoplasm, predominantly affecting adolescents and young adults. "This second GWAS emphasizes the association of the CDKN2A/CDKN2B locus with osteosarcoma development in large and giant dog breeds." (PMID 37505880, 2023). "Using the same murine MSC model, we have previously published that these transformed murine MSCs, including those with loss of CDKN2A/CDKN2B, show hallmarks of osteosarcoma with a highly complex genome and many copy number alterations." (PMID 34921235, 2022). "In another study, we have demonstrated that mice injected with transformed murine MSCs, all with loss of CDKN2A/CDKN2B, formed osteosarcoma, with evident osteoid formation by atypical tumour cells." (PMID 34921235, 2022). "Interestingly, the chromosome 11 locus identified is located around the MTAP and CDKN2A/CDKN2B genes and overlaps with the CDKN2A/CDKN2B locus, which is associated with osteosarcoma in other GWASs." (PMID 37505880, 2023). "Interestingly, both studies reported a high frequency (30–41%) of individuals carrying mutations affecting the CDKN2A and CDKN2B genes previously associated with osteosarcoma risk." (PMID 37505880, 2023). "Thus, our results combined with previously published results, suggest that loss of CDKN2A/CDKN2B is an early driver event in osteosarcoma." (PMID 34921235, 2022). "Our results illustrate that loss of CDKN2A and/or CDKN2B are early events in the development of osteosarcoma, and that these events can be targeted by CDK4/CDK6 inhibition, which might be used as a novel therapeutic option in approximately 20–23% of the patients." (PMID 34921235, 2022). "In the current study, we investigate the role of the Cdkn2a/Cdkn2b genes in the spontaneous transformation of murine MSCs towards osteosarcoma." (PMID 34921235, 2022). "In human patients with soft tissue sarcomas, loss of CDKN2B and CDKN2A is associated with reduced survival, while in dogs, absence or reduced levels of p16INK4A have been reported in melanoma tumours and cell lines, as well as in osteosarcoma cell lines." (PMID 19643034, 2009). "The overlapping CDKN2A and CDKN2B genes and ANRIL are frequently deleted together in canine osteosarcoma." (PMID 30890123, 2019).
adenoma (7 papers, 2012 to 2025). A neoplasm arising from the epithelium. "Collectively, these findings suggest that reduced CDKN2B expression was associated with the severity of PHPT as reflected by the adenoma weight and serum PTH levels." (PMID 28600574, 2017). "Promoter hypermethylation of CDKN2A/p16 and CDKN2B/p15 is considerably more common in parathyroid carcinomas than in benign adenomas, and it shows a positive correlation with increased cell proliferation as indicated by Ki-67 overexpression." (PMID 41210508, 2025). "In contrast to previous studies, we found hypermethylation of cyclin dependent kinase inhibitors - CDKN2A and CDKN2B in about half of the adenomas." (PMID 28600574, 2017). "Sequencing analysis revealed that 47% (n = 14) of the adenomas were hypermethylated (>10% methylation density) in the CDKN2B promoter region with a mean methylation density of 24.8 ± 12% (11.5–58.3%)." (PMID 28600574, 2017). "CDKN2B, which was downregulated in our adenoma and colorectal tumor samples is also silenced by DNA methylation in a variety of haematological malignancies." (PMID 23049694, 2012). "ESR1 has been shown to occur in histologically normal colon epithelium in an age dependent fashion, CDH13 is also frequently methylated in CRC and seems to be correlated with the adenoma-carcinoma transition, like other genes with methylation frequencies > 30% (CDKN2B, RASSF1, RARB, APC and TIMP3)." (PMID 25091577, 2014). "In particular, higher methylation levels of CDKN2B, RASSF1, CHFR, BRCA2 and IGSF4 were observed in adenomas that recurred." (PMID 25091577, 2014). "Although the expression was reduced in approximately 85% of the adenomas, hypermethylation of CKDN2A and CDKN2B promoter regions was found in a much smaller proportion implying that other mechanism may be involved in CDKN2A and CDKN2Breduced expressions." (PMID 28600574, 2017). "In addition, the promoter regions of CDKN2A, CDKN2B, and of RASSF1A were significantly hyper-methylated in 50% (n = 15), 47% (n = 14), and 90% (n = 27) of adenomas respectively." (PMID 28600574, 2017).
lung adenocarcinoma (6 papers, 2017 to 2025). A carcinoma that arises from the lung and is characterized by the presence of malignant glandular epithelial cells. "Homozygous deletion (HD) of CDKN2A and CDKN2B (CDKN2A/BHD) is the most frequent copy‐number variation (CNV) in lung adenocarcinoma (LUAD)." (PMID 35253368, 2022). "Only two clinically actionable genes—CDKN2A and CDKN2B—had lower frequencies of alteration in protocol patients with lung adenocarcinoma." (PMID 32914008, 2019). "Knowledge of the roles of CDKN2A and CDKN2B HD in lung adenocarcinoma (LUAD) is scarce." (PMID 35253368, 2022).
Obesity (6 papers, 2014 to 2025). Accumulation of substantial excess body fat. "Altered expression of a neighboring gene, CDKN2B, has been also recognized to correlate with obesity and hepatic steatosis in people carrying the risk SNPs." (PMID 38891115, 2024). "CDKN2B expression was regulated by obesity status, and this effect was stronger in carriers of 9p21 risk alleles." (PMID 24680834, 2014). "The genes neighboring ANRIL have also been reported to have a role in metabolic regulation, as CDKN2B is highly expressed in subcutaneous adipose tissue (SAT), with the levels positively correlating with obesity and hepatic steatosis in 9p21.3 risk allele carriers." (PMID 38891115, 2024). "The known anti-proliferative effects of CDKN2B, its high expression in SAT and its link to obesity suggest that this gene is involved in the regulation of SAT growth and expandability in response to changes in energy balance." (PMID 24680834, 2014). "GCKR, ABCB11, CDKAL1, CDKN2B, NT5C2, and APOC1 were associated with metabolically unhealthy phenotypes in individuals with normal weight but not in those with obesity." (PMID 33500527, 2021). "GCKR, ABCB11, CDKAL1, CDKN2B, NT5C2, and APOC1 were associated with metabolically unhealthy in individuals with normal weight but not in those with obesity." (PMID 33500527, 2021). "In view of the association between obesity and CVD, which is independent of conventional CVD risk factors, we pursued the investigation of CDKN2B expression in adipose tissue further." (PMID 24680834, 2014). "He found GCKR, ABCB11, CDKAL1, CDKN2B, NT5C2, and APOC1 gene were associated with metabolically unhealthy phenotypes in individuals with normal weight but not in those with obesity, showing that certain genetic polymorphisms may also have an impact on the metabolic health in NWO populations." (PMID 39777912, 2025).
Stroke (6 papers, 2009 to 2021). Sudden impairment of blood flow to a part of the brain due to occlusion or rupture of an artery to the brain. "Other candidate genes include Interleukin-6 (IL-6) and CDKN2A/CDKN2B which have been implicated as sources of the racial disparities in stroke incidence." (PMID 34828431, 2021). "To date, a stroke can be genetically associated with multiple susceptibility loci, including 9p21 (CDKN2A/CDKN2B/ANRIL), 7p21 (HDAC9), 6p21.1, 4p25 (PITX2), 16q22 (ZFHX3), 9q34 (ABO)." (PMID 33808851, 2021).
cervical cancer (5 papers, 2008 to 2016). A primary or metastatic malignant neoplasm involving the cervix. "Loss of RB1 function, which is a well known phenomenon in cervical cancer leads to expression of Cyclin D1, over-expression/amplification of CDK4, and/or loss of the CDKN1B, CDKN2A and CDKN2B." (PMID 26701206, 2016). "Significant promoter hypermethylation has been reported for both CDKN2A and CDKN2B in cervical cancer patients of North Indian origin." (PMID 24790823, 2014). "Decreased expression of CDKN2B has not been found due to copy number loss or mutation in cervical cancer." (PMID 18248679, 2008). "We also found CDKN2B to be over expressed in all CIN I, two CIN II and one CIN III however, greater than four fold decrease in cervical cancer (T1) was observed." (PMID 18248679, 2008). "It has been reported that cervical cancers and CIN III lesion have elevated levels of CDKN2B (84% and 79%, respectively)." (PMID 18248679, 2008).
mesothelioma (5 papers, 2008 to 2022). A usually malignant and aggressive neoplasm of the mesothelium which is often associated with exposure to asbestos. "In human mesotheliomas, deletions of the Cdkn2a/Arf and Cdkn2b gene loci associated with hypermethylation are reported to be common at the NF2 gene locus." (PMID 18795165, 2008). "Another work studied CNVs in 22 mesothelioma patients and identified lost copies of CDKN2A and CDKN2B tumor suppressor genes." (PMID 26185765, 2015).
multiple myeloma (5 papers, 2017 to 2024). "The methylation loss of CDKN2A and CDKN2B is demonstrated in myeloma patients." (PMID 32633782, 2020). "In multiple myeloma (MM), a cancer affecting plasma cells, several tumor suppressor genes (e.g., CDKN2A, CDKN2B, SOCS1, and SHP1) are hypermethylated in the CpG islands of their promoters, leading to gene translation inhibition." (PMID 38248418, 2024).
open-angle glaucoma (5 papers, 2012 to 2024). Chronic outflow obstruction of the eye's drainage canals that can lead to increased internal eye pressure and optic nerve damage. "Interestingly, genome-wide association studies have identified CDKN2b polymorphisms as associated with either increased or decreased risk of open-angle glaucoma." (PMID 37762022, 2023). "Interestingly, a case–control study conducted on patients with primary open-angle glaucoma (POAG) concludes that the carriers of polymorphism in miR-182 and CDKN2B genes have an increased risk of developing POAG." (PMID 34222230, 2021).
thyroid cancer (5 papers, 2018 to 2024). "Another important senescence marker, CDKN2B, was highly expressed in adrenal medullary tumor samples obtained by nuclei isolation as well as in thyroid carcinoma samples obtained by an enzymatic approach." (PMID 39839668, 2024). "Besides, the bioinformatic analysis found that genes related to the cell cycle (i.e., CDKN2A, CDKN2B, CCNE1, etc.)were mutated or abnormally expressed in ATC, which might provide another thought in advanced thyroid cancers." (PMID 34900720, 2021).
breast tumors (4 papers, 2013 to 2016). "The circuit formed by MYC and the pair CDKN2A/CDKN2B also appears very significant in breast tumors, in coherence with the role that MYC amplification has on the enhancement of cell cycle de-regulation." (PMID 26792175, 2016). "For example, a low rate of promoter methylation was observed for the TUSC3 (9/105 samples), MGMT (8/105 samples) and CDKN2B (2/105 samples) genes in breast tumors." (PMID 23472065, 2013). "To test this hypothesis, we investigated associations between rs11515 genotypes and expression of CDKN2A (transcripts, p16INK4a and p14ARF), and CDKN2B in 25 breast tumors (12 from women with the CG genotype and 13 with the CC genotype)." (PMID 26835415, 2015).
renal cell carcinoma (4 papers, 2019 to 2024). "Previous study revealed that mutation of CDKN2B lead to an increased incidence of renal cell carcinoma." (PMID 36776317, 2023). "However, renal cell carcinoma lesions have not been detected in Xenopus tropicalis with cdkn2b knockout." (PMID 39659584, 2024).
soft tissue sarcoma (4 papers, 2009 to 2025). A malignant neoplasm arising from muscle tissue, adipose tissue, blood vessels, fibrous tissue, or other supportive tissues excluding the bones. "CDKN2A/CDKN2B DNA copy number aberrations have been reported to be highly prevalent in MPNST, myxofibrosarcoma, and undifferentiated pleomorphic sarcomas and were associated with a poor prognosis in soft tissue sarcomas." (PMID 40548109, 2025).
endometrial carcinoma (3 papers, 2016 to 2022). A malignant tumor arising from the epithelium that lines the cavity of the uterine body. "We evaluated whether rs17761446 worked as a cis-regulatory element of ANRIL, CDKN2A, and CDKN2B with the allele specific expression (ASE) analysis using eutopic endometrial tissues and endometrial carcinoma cell lines." (PMID 27055116, 2016). "The first gene regulates some onco-suppressors such as CDKN2B, CDKN2A and ARF; its inactivation has been correlated with the development of endometriosic foci and endometrial carcinoma." (PMID 32143537, 2020).
esophageal cancer (3 papers, 2012 to 2024). A primary or metastatic malignant neoplasm involving the esophagus. "In esophageal cancers, CDKN2A, CDKN2B, and CCND1 alterations in the cell cycle pathway were frequently observed." (PMID 38672586, 2024).
familial melanoma (3 papers, 2020 to 2025). Familial melanoma (FM) is a rare inherited form of melanoma characterized by development of histologically confirmed melanoma in two first degrees relatives or more relatives in an affected family. "The tumor suppressors p16 (CDKN2A) and p15 (CDKN2B) (encoded by the familial melanoma CDKN2 locus) inhibit CDK4/6 activity and have important roles in cellular senescence." (PMID 32067956, 2020).
Hepatic steatosis (3 papers, 2014 to 2025). Steatosis is a term used to denote lipid accumulation within hepatocytes. "Using serum alanine aminotransferase (S-ALAT) as a marker, we found evidence of a relationship between CDKN2B expression in SAT and hepatic steatosis, since S-ALAT was positively correlated with CDKN2B expression, also after BMI adjustment." (PMID 24680834, 2014). "CDKN2B expression in SAT correlated with indicators of ectopic fat accumulation, including markers of hepatic steatosis." (PMID 24680834, 2014).
lung squamous cell carcinoma (3 papers, 2017 to 2024). "Copy number loss of CDKN2B predicts poor survival in patients with lung squamous cell carcinoma." (PMID 28881680, 2017).
medulloblastoma (3 papers, 2009 to 2018). A malignant, invasive embryonal neoplasm arising from the cerebellum. "Homozygous deletions of (i) the 9p21.1–p21.3 region encompassing CDKN2A, CDKN2B and ARF and (ii) the 6q23.1 region, each observed in a single cell line, have previously been reported in medulloblastoma and other cancer types." (PMID 19584924, 2009).
neurofibroma (3 papers, 2012 to 2019). An intraneural or extraneural neoplasm arising from nerve tissues and neural sheaths. "Recent cytogenetic data suggests that mutations in the CDKN2A and CDKN2B loci, which code for cell cycle regulators p16 and p14, accumulate as part of the “process” by which neurofibromas become malignant." (PMID 24216989, 2013). "The chromosome 9p21.3 region harbours a cluster of important growth regulatory genes (CDKN2A/ARF and CDKN2B) that are deleted or transcriptionally silenced in a wide range of tumours such as plexiform neurofibromas (PNF)." (PMID 23101500, 2012). "Furthermore, the silencing or homozygous deletion of CDKN2A, ARF, and CDKN2B has been detected in a subset of PNF, atypical neurofibromas, as well as MPNSTs, indicating that these genes have a role not only in the formation of PNFs, but probably also in MPNST development." (PMID 31694342, 2019).
pancreatic adenocarcinoma (3 papers, 2016 to 2022). "In fact, CDKN2B and HNF1A deletions/inactivations have been evidenced in pancreatic adenocarcinoma." (PMID 34668636, 2022).
retinoblastoma (3 papers, 2009 to 2015). A malignant tumor that originates in the nuclear layer of the retina. "CDKN2B (p15), a cyclin dependant kinase inhibitor type 2B gene, acts as a tumour suppressor in the retinoblastoma pathway." (PMID 25798827, 2015).
/T-cell lymphoma (2 papers, 2011 to 2013). "Various tumour suppressor genes have been shown to be frequently hypermethylated in NK/T-cell lymphoma including p73, CDKN2A, CDKN2B, hMLH1 and RARβ, but hypermethylation of miR-124-1 is one of the first reports of methylation of miR in NK/T-cell lymphoma." (PMID 21544199, 2011).
acute promyelocytic leukemia (2 papers, 2011 to 2022). An aggressive form of acute myeloid leukemia (AML), characterized by arrest of leukocyte differentiation at the promyelocyte stage, due to a specific chromosomal translocation t(15;17) in myeloid cells. "For example, CDKN2B methylation has negative prognostic impact on newly diagnosed acute promyelocytic leukemia patients." (PMID 35854240, 2022).
aneurysm (2 papers, 2018 to 2022). Bulging or ballooning in an area of an artery secondary to arterial wall weakening. "Knockout mice lacking CDKN2B do not only develop a cancer-related phenotype but also advanced aneurysms, accelerated smooth muscle cell apoptosis and medial arterial thinning, suggesting a potential involvement of CDKN2B not only in cancer but also in vascular disease." (PMID 29868613, 2018).
biliary tract cancer (2 papers, 2024 to 2026). "In biliary tract cancers, CDKN2A and CDKN2B alterations in the cell cycle pathway were observed; however, these are not effective therapeutic target genes." (PMID 38672586, 2024).
brain tumor (2 papers, 2021 to 2023). "In the frame of brain tumors, CDKN2B and/or CDKN2A mutations are among the most frequent events seen in 50%–60% of all GBMs." (PMID 38188342, 2023).
cholangiocarcinoma (2 papers, 2021 to 2022). A carcinoma that arises from the intrahepatic biliary tree (intrahepatic cholangiocarcinoma) or from the junction, or adjacent to the junction, of the right and left hepatic ducts (hilar cholangiocarcinoma). "In conclusion, our data revealed that miR-29b acts as a tumor suppressor in cholangiocarcinoma by promoting CDKN2B demethylation and transcription via suppression of DNMT3B activity." (PMID 33601338, 2021). "Taken together, these results suggest that miR-29b acts as a tumor suppressor in cholangiocarcinoma by downregulating DNMT3B and promoting the expression of CDKN2B." (PMID 33601338, 2021).
chondrosarcoma (2 papers, 2008 to 2016). A malignant cartilaginous matrix-producing mesenchymal neoplasm arising from the bone and soft tissue. "Frequent loss of chromosome arm 9p has previously been described in chordomas, and particularly, the region covering the CDKN2A (p16 and p14) and CDKN2B (p15) loci in chromosomal band 9p21 has been shown to be deleted in many tumour types, also in chondrosarcoma." (PMID 18071362, 2008).
colorectal adenoma (2 papers, 2014 to 2025). An adenoma that arises from the colon or rectum. "In the present study, CDKN2B expression was found to be downregulated in CRC tissues, which is consistent with the transcriptome profile of colorectal adenomas." (PMID 25202407, 2014).
colorectal tumor (2 papers, 2012 to 2018). "In addition, immunohistochemistry analyses revealed that EZH2 was upregulated in colorectal tumor tissues, whereas KLF2 and CDKN2B expression was reduced in cancer tissues." (PMID 30266084, 2018).